LMX1A (LIM homeobox transcription factor 1 alpha)
Description:
Acts as a transcriptional activator by binding to an A/T-rich sequence, the FLAT element, in the insulin gene promoter. Required for development of the roof plate and, in turn, for specification of dorsal cell fates in the CNS and developing vertebrae (By similarity).
Synonyms: LMX1.1; DFNA7; LMX1
Tractability: PROTAC: ubiquitination databases record sites on it.
Gene: Protein-coding gene on chromosome 1 (165,201,867 to 165,356,715, reverse strand). Ensembl gene ENSG00000162761.
Subcellular location: Nucleus
Subcellular location (Human Protein Atlas): Golgi apparatus; Nucleoplasm; Vesicles
Gene Ontology:
Molecular function: protein binding; sequence-specific double-stranded DNA binding; DNA-binding transcription activator activity, RNA polymerase II-specific; DNA-binding transcription factor activity, RNA polymerase II-specific; RNA polymerase II transcription regulatory region sequence-specific DNA binding; DNA binding
Biological process: dopaminergic neuron differentiation; midbrain dopaminergic neuron differentiation; neuron differentiation; positive regulation of transcription by RNA polymerase II; regulation of transcription by RNA polymerase II; regulation of DNA-templated transcription; synapse organization
Cellular component: chromatin; nucleus
Genetic constraint (gnomAD): Loss-of-function variants: 15 observed, 48.49 expected, observed/expected ratio (o/e) 0.31, 90% interval 0.21 to 0.48. The upper end of that interval is the gene's LOEUF score, 0.48, which puts it in group 2 of 6, group 1 being the genes least tolerant of losing a copy. Missense variants: 363 observed, 490.54 expected, observed/expected ratio (o/e) 0.74, 90% interval 0.68 to 0.81. Synonymous variants: 165 observed, 194.76 expected, observed/expected ratio (o/e) 0.85, 90% interval 0.75 to 0.96.
Gene-disease validity (ClinGen):
ClinGen rates the evidence that LMX1A causes each of these diseases.
autosomal dominant nonsyndromic hearing loss (autosomal dominant): Definitive. Autosomal dominant form of nonsyndromic deafness.
Homologues: Orthologues: chimpanzee LMX1A (100% identical), macaque LMX1A (100% identical), dog LMX1A (98% identical), rabbit LMX1A (98% identical), guinea pig LMX1A (98% identical), pig LMX1A (98% identical), rat Lmx1a (97% identical), mouse Lmx1a (97% identical), tropical clawed frog lmx1a (76% identical), zebrafish lmx1al (61% identical). Paralogues in human: LMX1B (68% identical), LHX3 (32% identical), LHX4 (30% identical), LHX1 (30% identical), ZFHX4 (30% identical), ZFHX3 (29% identical), LHX5 (28% identical), LHX6 (26% identical), LHX9 (26% identical), LHX2 (25% identical), LHX8 (25% identical), ZFHX2 (25% identical), and 8 more.
Diseases named in the same sentence as LMX1A in open-access papers:
LMX1A is named in the same sentence as 63 diseases in open-access papers, as found by Europe PMC text mining. Sharing a sentence is not in itself a finding about the gene and the disease. The quoted sentences say what the papers report.
Parkinson disease (14 papers, 2009 to 2026). A progressive degenerative disorder of the central nervous system characterized by loss of dopamine producing neurons in the substantia nigra and the presence of Lewy bodies in the substantia nigra and locus coeruleus. "Another combination of NeuroD1, Ascl1, Lmx1a, and miR218 can produce dopaminergic neurons from astrocytes in an in vivo Parkinson’s disease mouse model." (PMID 31231645, 2019). "In cell cultures, Ascl1, Nurr1, and Lmx1a can induce dopaminergic neurons from fibroblasts derived from Parkinson’s disease patients." (PMID 31231645, 2019). "Crucially, the transcriptomic fingerprint of human astrocytes derived from LMX1A-expressing midbrain progenitors reported here offers a much-needed resource for assessing the authenticity of stem cell-derived astrocytes in studies of Parkinson’s disease." (PMID 41150379, 2025). "Relevantly, homozygous conditional knockout of both Lmx1b and Lmx1a as well as siRNA knockdown of Lmx1b alone impact mitochondrial functions in neurons and may contribute to Parkinson’s disease." (PMID 39829808, 2025). "For example, LMX1A and CHCHD2 have been previously associated with Parkinson’s disease." (PMID 38697975, 2024). "Regarding applying astrocyte transdifferentiation in Parkinson’s disease, one group used NeuroD1, Ascl1, Lmx1a, and miR-218 to convert astrocytes into dopaminergic neurons in the striatum of PD model mice, and the motor behavior symptoms of the mice were improved." (PMID 36138912, 2022). "Ascl1 has also been combined with Lmx1a and Nurr1 (ALN) to convert endogenous NG2 glia to inhibitory iNs in a dopamine-depleted (6-OHDA treated) mouse model of Parkinson’s disease." (PMID 34291049, 2021). "In contrast, the combination of a slightly different combination of TFs (Ascl1, NeuroD1, Lmx1a) and miR-218 efficiently programmed striatal astrocytes into functional induced dopaminergic neurons (iDANs), also in a 6-OHDA model of Parkinson’s disease." (PMID 34291049, 2021). "A series of genes, including mCherry and various combinations of the neural transcription factors LMX1a, FOXA2 and OTX2, were inserted in recipient cell lines derived from H9 ESC, as well as iPSC lines derived from a Parkinson’s disease patient and a normal sibling control." (PMID 24304893, 2014). "For example, in a mouse model of Parkinson’s disease, delivery of an adenovirus construct by CRISPR-SAM via injection into the brain resulted in successful reprogramming of astrocytes into functional neurons through the activation of differentiation factors Ascl1, Lmx1a, and Nr4a2." (PMID 40650152, 2025).
glioma (12 papers, 2012 to 2025). A benign or malignant brain and spinal cord tumor that arises from glial cells (astrocytes, oligodendrocytes, ependymal cells). "SCAMP1 also suppresses the malignant proliferation of glioma cells through the miR-499a-5p/LMX1A/NLRC5 axis, highlighting SCAMP1 as an oncogene." (PMID 33493138, 2021). "documented that miR-499a-5p inhibited LMX1A-mediated malignant behavior by directly targeting LMX1A-3′-UTR in glioma cells." (PMID 33575204, 2020). "These evidence indicated that LMX1A played a cancerogenic role in malignant progression of glioma cells." (PMID 31207033, 2019). "In conclusion, our study clarifies that SCAMP1/miR‐499a‐5p/LMX1A/NLRC5 axis plays a critical role in modulating malignant progression of glioma cells, which provide a novel therapeutic strategy for glioma treatment." (PMID 31207033, 2019). "Transcription factor LIM homeobox transcription factor 1, alpha (LMX1A) was overexpressed in glioma tissues and cells." (PMID 31207033, 2019). "Results showed that down‐regulation of miR‐499a‐5p expression dramatically reversed the suppressive effect on LMX1A by SCAMP1 knockdown in glioma cells." (PMID 31207033, 2019). "Overall, evidence above revealed that miR‐499a‐5p suppressed the expression of NLRC5 by reducing LMX1A in glioma cells." (PMID 31207033, 2019). "Furthermore, overexpression of LMX1A rescued the tumour‐suppressive impacts of overexpressed miR‐499a‐5p on glioma cells via up‐regulating NLRC5 expression." (PMID 31207033, 2019). "Hence, down‐regulation of SCAMP1 remarkably reduced the expression level of LMX1A, indicating that LMX1A participated in miR‐499a‐5p‐induced tumour‐suppressive effects on glioma cells." (PMID 31207033, 2019). "Hence the LMX1A expression of glioma cells altered SCAMP1 and miR‐499a‐5p expression was firstly detected." (PMID 31207033, 2019). "Furthermore, the expression of LMX1A in glioma cells co‐transfected with sh‐SCAMP1 and miR‐499a‐5p agomir or antagomir was examined." (PMID 31207033, 2019). "SCAMP1 could increase LMX1A by negative regulating miR‐499a‐5p expression in glioma cells." (PMID 31207033, 2019). "In addition, our research showed LMX1A was overexpressed in glioma tissues and cell lines, meanwhile, up‐regulation of LMX1A significantly enhanced the proliferation, migration and invasion as well as suppressed apoptosis, implying that LMX1A exerts oncogenic effects on glioma cells." (PMID 31207033, 2019). "LMX1A was found to be a downstream target of miR-499a-5p and participated in lncRNA SCAMP1-induced oncogenesis in glioma." (PMID 35992869, 2022). "In this type of tumor, LMX1A activates NLRC5 expression, stimulating the Wnt/β-catenin signaling pathway, which promotes malignancy of the glioma cells." (PMID 35054945, 2022). "LMX1A can regulate the expression of NLRC5 (NLR family, CARD domain containing 5) and activate Wnt/β-catenin signaling pathway in glioma." (PMID 35992869, 2022). "This suggests that NLRC5 plays a regulatory role in the development of glioma and is related to IFN signaling and the SCAMP1/miR-499a-5p/LMX1A/NLRC5 pathway." (PMID 34220868, 2021). "Tsai and his colleagues reported that the higher expression of LMX1A shown by immunohistochemical staining correlated with the WHO grade of meningioma and glioma." (PMID 32751497, 2020). "In conclusion, the SCAMP1/miR‐499a‐5p/LMX1A/NLRC5 axis serves as a critical regulator of tumourigenesis and progression of glioma, providing a novel therapeutic strategy for glioma treatment." (PMID 31207033, 2019). "The genes RRM2, KIAA0101, UBE2C, LMX1A, DTL, and LBX1 demonstrated significant overexpression in all human glioma subtypes (GBM, ODG, OA, AA) with a p-value ≤ 0.0001." (PMID 31475119, 2019). "LMX1A transcriptionally activates the NLRC5 expression, which promotes the malignant biological behaviours of glioma cells through stimulating Wnt/β‐catenin signalling pathway." (PMID 31207033, 2019).
glioma (continued). "LMX1A and NLRC5 were highly expressed in glioma tissues and cell lines, knockdown of LMX1A or NLRC5 obviously impeded the malignant progression of glioma cells." (PMID 31207033, 2019). "Furthermore, glioma cells exhibit upregulation of SCAMP1, a sponge lncRNA that binds to miR-499, avoiding LMX1A repression." (PMID 35054945, 2022). "Overall, miR‐499a‐5p could negatively regulate the expression of LMX1A, which directly bound to NLRC5 promoter and modulated its expression, then suppressed the biological behaviours of glioma cells." (PMID 31207033, 2019). "The previous results uncovered that LMX1A exerted cancerogenic functions in glioma cells, however whether LMX1A was involved in SCAMP1 and miR‐499a‐5p regulatory malignant progression of glioma cells remains blurry." (PMID 31207033, 2019). "In our study, the expression levels of SCAMP1, miR‐499a‐5p, LMX1A and NLRC5 were investigated in glioma tissues and cell lines, meanwhile, the effects on regulating malignant progression of glioma and cross‐talk among SCAMP1, miR‐499a‐5p, LMX1A and NLRC5 were completely clarified." (PMID 31207033, 2019). "Consequently, the molecular mechanism revealed that knockdown of SCAMP1 increased miR‐499a‐5p expression, which hindered the expression of LMX1A and NLRC5, further led to carcinostatic effects on glioma cells by repressing the activity of Wnt/β‐catenin signalling pathway." (PMID 31207033, 2019). "Therefore, data above clarified that LMX1A knockdown obviously attenuated the activity of Wnt/β‐catenin signalling pathway by down‐regulating NLRC5 expression and restrained malignant behaviours of glioma cells." (PMID 31207033, 2019).
cervical cancer (9 papers, 2012 to 2024). A primary or metastatic malignant neoplasm involving the cervix. "The relative expression levels of miR-142-5p and LMX1A in cervical cancer tissues and cells were evaluated by qRT-PCR." (PMID 33585699, 2021). "The use of differential methylation hybridization using a pilot methylation array allowed the identification of SOX1, NKX6-1, PAX1, WT1, and LMX1A as frequently methylated genes in cervical cancer and precursor lesions." (PMID 34790573, 2021). "We found that miR-142-5p expression was elevated but LIM homeobox transcription factor 1 alpha (LMX1A) was decreased in cervical cancer tissues and cells." (PMID 33585699, 2021). "Recently, LMX1A was shown to be hypermethylated and functioned as a tumor suppressor in cervical cancer, ovarian cancer, and gastric cancer." (PMID 32751497, 2020). "LMX1A is a suppressor of tumorigenesis and metastasis of cervical cancer; however, the regulation of LMX1A during tumorigenesis remains to be understood." (PMID 32328088, 2020). "Recently, LMX1A has been found to be hypermethylated in cervical cancer, gastric cancer, bladder cancer, ovarian cancer, and colorectal cancer." (PMID 32751497, 2020). "Hypermethylation of ADAMTS6 is identified in multiple cancers, and its methylation level continuously decreased in mCHG, while LMX1A continuously increased in mCHG and serve as a DNA methylation marker in cervical cancer." (PMID 32258002, 2020). "In previous studies, we discovered that SOX1, NKX6-1, PAX1, WT1, and LMX1A are highly methylated in cervical cancer." (PMID 22815913, 2012). "The differential methylation hybridization (DMH) using a pilot methylation array identified SOX1, NKX6-1, PAX1, WT1, and LMX1A as frequently methylated genes in cervical cancer and its precursor lesions." (PMID 22815913, 2012). "The results demonstrated that miR-142-5p expression levels were significantly higher (P < 0.001) and LMX1A expression levels were significantly lower (P < 0.01) in the cervical cancer tissues and cells compared with paracarcinoma tissues and normal cervical epithelial cell line Ect1/E6E7." (PMID 33585699, 2021). "LMX1A was also identified as a metastasis suppressor in cervical cancer." (PMID 33585699, 2021). "To evaluate whether the expression of LMX1A was able to regulate migration and invasion of cervical cancer cells, we performed transwell assays to determine migration and invasion abilities of HeLa cells." (PMID 33585699, 2021). "Taken together, our study indicated that miR-142-5p may play an onco-miRNA role in the progression of cervical cancer via LMX1A-mediated Wnt/β-catenin-signaling pathway." (PMID 33585699, 2021). "In a previous study, we demonstrated that LMX1A could suppress cervical cancer invasion through an incomplete EMT." (PMID 32751497, 2020). "LMX1A has been recently reported to be hypermethylated in cervical cancers." (PMID 32328088, 2020). "LMX1A is hyper-methylated and downregulated in ovarian cancer and cervical cancer." (PMID 31822638, 2019). "Similar to these study, the present data demonstrated that LMX1A was decreased in cervical cancer and cell lines, LMX1A induced apoptosis and inhibited proliferation, invasion, and migration of HeLa cells, indicating the potential tumor suppressor role of LMX1A in the development of cervical cancer." (PMID 33585699, 2021). "Therefore, we speculate that miR-142-5p can regulate the development of cervical cancer by targeting LMX1A mediated Wnt/β-catenin-signaling pathway." (PMID 33585699, 2021). "Our research group has reported that LMX1A was methylation-silenced and that the expression of LIMX1A inhibited colony formation and invasion in cervical cancer." (PMID 32751497, 2020). "Previously, in addition to identifying DNA methylation biomarkers, we also revealed that LMX1A and SOX1 were tumor suppressor genes in cervical cancer and hepatocellular carcinoma." (PMID 31547144, 2019).
cervical cancer (continued). "In a previous study, we showed that LMX1A could suppress the EMT pathway partially by inhibition of the EMT-related transcription factors SNAIL, SLUG, and TWIST in cervical cancer." (PMID 32751497, 2020).
deafness (9 papers, 2018 to 2025). An inherited or acquired condition characterized by the complete loss of the ability to hear from one or both ears. "Several human mutations in LMX1A have been associated with hearing loss, but the exact cellular mechanisms of deafness are unclear." (PMID 40109362, 2025). "Together, these results suggest that alterations in LMX1A are associated with dominantly inherited asymmetric deafness." (PMID 36140227, 2022). "Bi-allelic deleterious variants of Lmx1a are associated with a complex phenotype in mice, including deafness and vestibular defects, due to arrest of inner ear development." (PMID 29754270, 2018). "The results showed that in the absence of Lmx1a, the endocochlear potential is abolished, explaining the previously published profound deafness in the Lmx1a null mutant." (PMID 40109362, 2025). "In the present study, we identified pathogenic missense variants of LMX1A (MIM: 600298), a gene associated with a complex phenotype in mice, including recessive deafness and vestibular defects, as a cause of dominant NSHI and vestibular dysfunction in humans." (PMID 29754270, 2018). "They found that numerous deafness-related genes (e.g. Col9a2, Lmx1a, and Sox10) were downregulated, and single-cell transcriptome data from Chd7KO/+ organoids also showed that some deafness-related genes (e.g. Six1, Ush1c, and Strc) were downregulated in HCs, implying that." (PMID 38015350, 2024).